BMP2 (bone morphogenetic protein 2)
Diseases named in the same sentence as BMP2 in open-access papers (continued):
Sharing a sentence is not in itself a finding about the gene and the disease.
neurofibroma (1 paper, 2016). An intraneural or extraneural neoplasm arising from nerve tissues and neural sheaths. "The role of BMP2 in progression to MPNSTs is evident by changes in its expression levels at various stages of neurofibroma development in clinical specimens." (PMID 27494873, 2016). "As expression of Bmp2 positively correlates with malignancy in neurofibromas, increased expression of BMP2 in MPNSTs may promote metastatic characteristics such as cell migration and invasion." (PMID 27494873, 2016). "Additionally, these data corroborate gene expression profiling of MPNST patient tissue samples by an independent group in which we found that BMP2 is up-regulated in MPNSTs as compared to other benign forms of neurofibromas that are typically heterozygous for Nf1." (PMID 27494873, 2016). "Our data mining of publicly available transcriptional profiling of NF1 syndrome-related clinical specimens demonstrated that Bmp2 expression was significantly higher in plexiform neurofibromas and MPNST patient samples, as compared to the benign forms of neurofibromas." (PMID 27494873, 2016).
oral squamous cell carcinoma (1 paper, 2016). "According to a recent report, excessively high doses of BMP-2 may cause oral squamous cell carcinoma." (PMID 27446821, 2016).
Osteoblastoma (1 paper, 2013). A rare benign bone-forming neoplasm usually arising from the spine. "Indeed, Wnt/beta-catenin target genes involved in bone metabolism, such as BMP2, BMP4, PTGS2 and MMP16, showed high expression levels in osteoblastoma." (PMID 24236197, 2013).
osteoradionecrosis (1 paper, 2023). Necrosis of bone following radiation injury. "Despite its limitations, this study showed the encouraging effects of Anatolian propolis on bone regeneration markers BMP-2 and TGFβ-3 in a radiotherapy-induced osteoradionecrosis model." (PMID 37909529, 2023).
pheochromocytoma (1 paper, 2012). "Our data demonstrated that hADMPCs, when exposed to oxidative stress, facilitate neuronal differentiation in rat pheochromocytoma cell line PC12 cells by upregulation of fibroblast growth factor 2 (FGF2) and bone morphogenetic protein 2 (BMP2) secretion through p38 MAPK activation." (PMID 22870983, 2012).
Pilomatricoma (1 paper, 2024). "The presence of Osteopontin and BMP‐2 expression in shadow cells or ghost cells provides further evidence supporting their role in the formation of areas of calcification and ossification within Pilomatricoma." (PMID 39139622, 2024).
pituitary adenomas (1 paper, 2013). "The role of BMP2, BMP4 and BMP7 as signalling peptides in the programming of pituitary development makes them plausible candidates for pituitary disorders including congenital insufficiency as well as pituitary adenomas." (PMID 24289245, 2013).
pituitary insufficiency (1 paper, 2013). "So, the aim of our study was to investigate whether genetic variants in BMP2, BMP4 and/or BMP7 are associated with congenital pituitary insufficiency." (PMID 24289245, 2013). "However, systematic search for mutations in BMP2, 4 and 7 in patients with combined pituitary insufficiency has not been performed yet." (PMID 24289245, 2013).
Pseudoarthrosis (1 paper, 2022). A pathologic entity characterized by a developmental defect in a long bone leading to bending and pathologic fracture, with inability to form a normal bony callus with subsequent fibrous nonunion, leading to the pseudarthrosis (or "false joint"). "For lumbar SF procedures, the highest percentages of subsidence and pseudoarthrosis were observed with PEEK filled with bone morphogenetic protein 2 (BMP2) and βTCP." (PMID 36362508, 2022).
psoriasis (1 paper, 2021). An autoimmune condition characterized by red, well-delineated plaques with silvery scales that are usually on the extensor surfaces and scalp. "Our findings highlight the regulatory role of miR-378a in the pathogenesis of psoriasis and prove that it directly binds to BMP2 gene, offering a novel target for miR-378a-mediated psoriasis." (PMID 34244572, 2021). "However, the mechanism underlying the down-regulation of BMP2 in psoriasis has not been fully clarified." (PMID 34244572, 2021).
pterygium (1 paper, 2021). A wedge-shaped fibrovascular lesion arising from the bulbar conjunctiva and extending to the cornea. "Our further analysis of pathways controlled by upstream regulator TP63 suggested increased EMT in pterygium, regulated by BMP2, BMP6, SNAI1 and KLF7." (PMID 34769520, 2021). "Elevated expression of BMP6 was previously shown in pterygium We observed modest upregulation of BMP2 in both pterygium subtypes, but BMP6 was upregulated only in pterygium-NE." (PMID 34769520, 2021). "An increase in EMT in corneal epithelium in pterygium is also suggested, regulated by KLF7, BMP2, BMP6, and SNAI1." (PMID 34769520, 2021).
renal dysfunction (1 paper, 2022). "The imbalance between BMP-2 and BMP-7 in the kidney is reflected as albuminuria, supporting the link between vascular and renal dysfunction." (PMID 36613483, 2022).
renal tumors (1 paper, 2026). "The association of bone formation with a favorable prognosis in renal tumors is unique, and BMP-2 may provide a potential explanation." (PMID 41523983, 2026).
rotator cuff tear (1 paper, 2022). "In a model of rotator cuff tear, an increase in BMP-2 after treatment, possibly benefitting the healing of the bone-tendon interface was reported." (PMID 35394237, 2022).
Rubinstein-Taybi syndrome (1 paper, 2017). A rare malformation syndrome characterized by congenital anomalies (microcephaly, specific facial characteristics, broad thumbs and halluces and postnatal growth retardation), short stature, intellectual disability and behavioral characteristics. "Precedent for this type of treatment exists, in theory, as in utero administration of BMP2/7 rescues the skeletal defects associated with a mouse model of Rubinstein-Taybi syndrome." (PMID 28166224, 2017).
sacroiliitis (1 paper, 2022). "Therefore, it is speculated that severe sacroiliitis, as detected on MRI, upregulates the level of the BMP-2 gene, which further leads to the formation of new bone." (PMID 35833133, 2022).
secondary pulmonary hypertension (1 paper, 2012). "Morrell and colleagues demonstrated that BMP-2 at doses of 1–100 ng/ml inhibited [3H] thymidine incorporation in PASMCs from normotensive and secondary pulmonary hypertension patients cultured in media that contained FBS." (PMID 22615735, 2012).
Sepsis (1 paper, 2024). Sepsis is defined as life-threatening organ dysfunction caused by a dysregulated host response to infection. "First, the identified sepsis-related pathways, such as BMP2 signaling and elastic fiber formation, would allow the development of therapeutic approaches in sepsis." (PMID 39566468, 2024).
soft tissue sarcoma (1 paper, 2016). A malignant neoplasm arising from muscle tissue, adipose tissue, blood vessels, fibrous tissue, or other supportive tissues excluding the bones. "Specifically, we investigated the role of high BMPR1A expression within the context of high BMP2 expression in soft tissue sarcomas and found a significant association with reduced disease free survival." (PMID 27114889, 2016). "This study suggests that BMPR1A-biased BMP2 signalling leads to disease progression in soft tissue sarcomas and that this outcome is linked to ECM remodelling." (PMID 27114889, 2016). "Herein, we sought to profile BMP type I receptor expression in soft tissue sarcomas in an attempt to explain the apparent dichotomy of BMP2 signalling." (PMID 27114889, 2016). "In the soft tissue sarcomas, BMP2 has long been suspected of playing a role in disease progression, but no definitive studies have been carried out." (PMID 27114889, 2016). "Thus, in addition to ECM remodelling and reduced bone formation, soft tissue sarcoma patients with BMPR1A-biased BMP2 expression are more likely to show tumour progression in the presence of high levels of endogenous BMP2." (PMID 27114889, 2016).
spasm (1 paper, 2019). "The results showed that BMP2 and GDNF expression was significantly decreased in the spasm segment compared with the normal colon and the distension segment." (PMID 31849612, 2019).
spinal stenosis (1 paper, 2023). Narrowing of the spinal canal. "Spinal stenosis was the most common diagnosis for the TCP + IBG group (48%), while spondylolisthesis was the most common primary diagnosis for the BMP-2 group (60%)." (PMID 37337174, 2023).
steatosis (1 paper, 2022). Increased lipid within the cytoplasm of cells. "In addition, a significant and progressive increase in serum BMP2 levels was found in NAFLD patients in relation to the histological grade of steatosis (p = 0.0032) and NAFLD activity score (p = 0.0081)." (PMID 35614516, 2022).
teratocarcinoma (1 paper, 2007). A germ cell tumor characterized by the presence of an embryonal carcinoma component and a teratoma component. "BMP2, belonging to the transforming growth factor superfamily, is involved in many important processes in early human and mouse development and have a variety of effects in human and mouse teratocarcinomas." (PMID 17442106, 2007).
tricuspid atresia (1 paper, 2025). Tricuspid atresia is (TA) a rare congenital heart malformation characterized by the congenital agenesis of tricuspid valve leading to severe hypoplasia of right ventricle (functionally univentricular). "Patients in Group 1, the tricuspid atresia group, carried variants in the BMP2, MYH6, NFATC1, NOTCH1, and ZFPM2 genes, which have been reported to be associated with tricuspid atresia." (PMID 41153298, 2025).
ulcerative colitis (1 paper, 2022). An inflammatory bowel disease involving the mucosal surface of the large intestine and rectum. "In ulcerative colitis (UC) patients, KLF4, CFTR, BMP2, TLR2 showed significantly lower expression in UC-associated cancer." (PMID 35733095, 2022).
ulcers (1 paper, 2021). "These products have been successful in regenerating bone and treating ulcers, respectively, but the amount of GF loaded (1.5 ​mg/ml BMP2 and 100 ​μg/g PDGF, respectively) far surpasses physiological levels of the GFs, resulting in side-effects such as ectopic bone formation and malignant growths." (PMID 33763641, 2021).
Ureteral obstruction (1 paper, 2023). Obstruction of the flow of urine through the ureter. "Moreover, BMP2 treatment in rats subjected to unilateral ureteral obstruction procedure reduced the intensity of collagen staining in the interstitial and tubular regions of the kidney." (PMID 38132468, 2023).
vitamin D deficiency (1 paper, 2025). A nutritional condition produced by a deficiency of VITAMIN D in the diet, insufficient production of vitamin D in the skin, inadequate absorption of vitamin D from the diet, or abnormal conversion of vitamin D to its bioactive metabolites. "To further explore the molecular impact of vitamin D deficiency on uterine function, we examined the expression of decidual marker genes, including Bmp2, Wnt4, Prl8a2, and Pgr, using qRT-PCR." (PMID 41292920, 2025).
xerostomia (1 paper, 2023). Dryness of the mouth resulting from reduced salivary secretion. "Although further detailed investigations on the role of BMP2 in salivary glands are required, this study provides the first evidence that BMP2 in salivary glands promotes an increase in the number of glandular acinar cells, which may help to improve xerostomia." (PMID 37033127, 2023).
Zinc deficiency (1 paper, 2025). A deficiency of the essential metal Zinc; an essential cofactor for many enzymes. "Zinc deficiency increases expression of bone morphogenetic proteins (BMP2, BMP4)." (PMID 41517264, 2025).
tumor (222 papers, 2004 to 2026). "This fibroblast population is regulated by BMP2 secreted by interferon‐associated basal‐like tumor cells." (PMID 40552583, 2025). "Subsequently, the subcutaneous tumor formation in nude mice also confirmed that BMP2 can reverse the growth inhibition caused by RUNX1 knockdown, and also reverse the reduction in vasculogenic mimicry density." (PMID 38610001, 2024). "Tumor-associated neutrophils expressing CCL2+ or CCL17+ promote BMP-2 and TGF-β2 secretion, thereby enhancing miR-301b-3p expression via paracrine signaling and activating the NF-κB signaling pathway." (PMID 38694506, 2024). "The BMP ligand BMP2 was the top upregulated gene in bone metastases, which has been shown to be secreted by macrophages, tumor-associated macrophages, and BC cells." (PMID 38193534, 2024). "Tumor-associated macrophages also were found to secrete BMP2 in the tumor microenvironment in breast cancer, which led to poor prognosis." (PMID 36353620, 2022). "On the other hand, BMP2 is usually upregulated in various, tumours and is associated with tumour progression." (PMID 36142232, 2022). "Previous studies have shown that upregulation of bone morphogenetic protein 2 (BMP-2) is associated with the occurrence of microcalcifications and tumor-associated macrophages (TAMs) in the tumor microenvironment can secrete BMP-2." (PMID 34983451, 2022). "Tumor-associated neutrophils produce large quantities of bone morphogenic protein (BMP)-2 and TGF-β2, which confer stem-like properties to these cancer cells." (PMID 33446717, 2021). "MMP1 and BMP2 are known to modulate cell activity and the tumor microenvironment, as well as being factors associated with OSCC relapse." (PMID 34445087, 2021). "A previous report linked BMP signaling with RUNX3 (a tumor suppressor) in colorectal carcinoma, where the BMP-2 and BMP-4-mediated upregulation of RUNX3 expression inhibited tumor progression." (PMID 32731498, 2020). "BMP2 has been implicated in promoting epithelial-to-mesenchymal transition and in inhibiting tumor cell apoptosis." (PMID 29670000, 2018). "A close association of BMP2 expression with bone metastasis of NPC has be verified in the present study, which indicates that BMP2 expression in primary tumor seems to correlate with the risk for accelerated bone metastasis formation in NPC patients." (PMID 28455969, 2017). "A significant association of BMP-2 mRNA expression was also found with advanced tumor stage and lymph node involvement, while lower BMP-2 mRNA expression was significantly associated with poor overall survival after radical nephrectomy." (PMID 25797254, 2015). "BMP2 can inhibit the progression of many different types of cancers but its role is also bi-directional since it is also implicated in tumor progression and angiogenesis in some cancers." (PMID 25070479, 2014). "Notably, one of the most highly upregulated secreted factor genes was GREM1 (encoding the BMP2/4/7 antagonist Gremlin1) which we have previously shown to play a role in MM tumour development in vivo." (PMID 40263435, 2025). "Furthermore, interferon‐associated basal‐like tumor cells secrete BMP2, which induces the expression and activity of NFE2L3, a transcription factor specific to MMP11+ mCAFs, promoting WNT5A expression." (PMID 40552583, 2025). "For current clinical application, we recognize that a low-dose and slow-release strategy of BMP-2 applied in bone regeneration is acceptable, even in the tumor-caused bone defects, while in the OS treatment, we still maintain a prudent stand to the employment of BMP-2." (PMID 34869325, 2021). "This reduced quantity, as well as the spatial control of the compound delivery, may decrease the risk of side effects that can be induced by a high dose of BMP-2, such as ectopic bone formation, inflammatory complication or tumor formation." (PMID 32911737, 2020). "However, human OSCC cell lines have been shown to express BMP-2 and be associated with rapid tumor growth in orthotopic animal model." (PMID 32188900, 2020).
tumor (continued). "Interestingly, a recombinant human version of BMP2 (rhBMP2) has found utility as a adjuvant in spinal surgery, but there remains concerns over its safety after heavy use was linked to new tumour formation." (PMID 27114889, 2016). "We focused on the genes that were upregulated in the LKB1 mutation group and positively correlated with BMP2 expression, since these genes might be responsible for BMP2-induced tumor progression in NSCLCs with LKB1 mutations." (PMID 26701726, 2016). "BMP-2 signaling is associated with poor prognosis and tumor progression." (PMID 24160469, 2013). "As ascites tumor cells are detached from the primary tumor site and may have acquired a metastatic potential, this observation suggests that BMP-2 may be associated or involved in the process of evading tumor cells from the primary site to the omentum." (PMID 19366455, 2009). "Moreover, BMP2 in the tumor microenvironment is also associated with NSCLC prognosis." (PMID 34136487, 2021). "In recent researches, it was reported that tumor-associated macrophages (TAMs) could secret TGFβ1 to promote LCSC properties by inducing EMT, and tumor-associated neutrophils (TANs) could secret TGFβ2 and BMP2, which induce miR-301b-3p and enhance stem cell characteristics in HCC." (PMID 33292618, 2020). "Previous studies support this finding, reporting osseous metaplasia in primary tumors with evidence of BMP-2 expression in the tumor or local stroma." (PMID 41523983, 2026). "Transcriptomic analysis revealed that ADX downregulated tumor-induced transcripts in bone by over 90%, including osteogenic (Lox, Sparcl1, Bmp2, Postn, and Col1a1) and pro-angiogenic (Bmper, Pecam-1, and Esam) signatures." (PMID 42149634, 2026). "Future studies should consider genetic perturbation strategies, such as CRISPR/Cas9‐mediated knockout or RNA interference, combined with lineage tracing, to more precisely delineate the role of BMP2 signaling in MMP11+ mCAF‐mediated tumor progression." (PMID 40552583, 2025). "Research has demonstrated that SPP2 can inhibit tumor growth and induce tumor apoptosis by eliminating the pro-tumor functions of bone morphogenetic protein 2 (BMP-2) signaling." (PMID 40052788, 2025). "BMP2 emerged as a potential driver of tumor progression, and its utility as a predictive or prognostic biomarker warrants further investigation in larger cohorts." (PMID 40936753, 2025). "Its induction by tumor-promoting cytokines, including bone morphogenetic protein 2 (BMP2) and tumor necrosis factor-α (TNF-α), further highlights its role in cell invasion and metastasis." (PMID 41011506, 2025). "The findings were supported by in vivo experiments, which showed that increasing the expression of BMP2 within liver tumors in mice promotes tumor growth and the spread of cancer cells to the lungs." (PMID 40136410, 2025). "Our data identified BMP2 as a potential driver of tumor progression, highlighting the need for additional studies in larger cohorts." (PMID 40936753, 2025). "We extracted total RNA from mouse tumor tissues using TRIzol and analyzed the correlation between H19, hsa-miR-138-5p, hsa-miR-22-3p, and BMP2 mRNA levels using qPCR." (PMID 40297808, 2025). "BMP2 expression correlates with GBM tumor malignancy and patient survival, suggesting its potential as a prognostic marker for human GBM." (PMID 40297808, 2025). "Mouse experiments confirmed that BMP2 promotes tumor progression, MMP11 expression, and angiogenesis." (PMID 40552583, 2025). "In contrast, inhibition of BMP signaling with Dorsomorphin mitigated tumor progression, indicating that BMP2 enhances tumor growth in vivo." (PMID 40552583, 2025). "Altogether, these data indicate that tumor-autonomous production of BMP2 and BMP7 synergize to maintain a quiescent-invasive niche in H3.3K27M DIPG." (PMID 39373720, 2024). "CD109 overexpression correlates with poor prognosis and promotes tumor cell migration via suppression of BMP-2-induced Smad1/5/9 phosphorylation." (PMID 39990858, 2024).